CXCL2 (C-X-C motif chemokine ligand 2)
Diseases named in the same sentence as CXCL2 in open-access papers (continued):
Sharing a sentence is not in itself a finding about the gene and the disease.
tumor (continued). "Single-cell transcriptional analysis of tumor cells revealed that several secreted factors involved in recruitment or chemotaxis of myeloid cells were increased, including Cxcl1, Cxcl2, Tgfβ3, and lactotransferrin (Ltf) after short-term Ab + Pal treatment." (PMID 31444334, 2019). "In mouse model of CRC, ablation of IL-17 resulted in reduced levels of CXCL1 and CXCL2, which correlates with decreased numbers of tumor infiltrating myeloid cells." (PMID 31775909, 2019). "In particular, the CXCR2-ligands CXCL5 and CXCL2 contribute to neutrophil accumulation and inhibit T-cell-dependent suppression of tumor growth." (PMID 31561620, 2019). "The increased binds of CXCL1 or CXCL2 to CXCR2 leads to reduced SAP18 expression under tumor conditions, which subsequently activates the ERK/STAT3 signaling pathway to promote mo-MDSCs accumulation." (PMID 31395859, 2019). "In turn, growth promoting factors including IL6, CCL2, VEGF, and CXCL2 are released from the osteoblasts, which promote tumor cell growth, again initiating an additional cycle." (PMID 29642534, 2018). "Snail knockdown reduces the expression of CXCR2 ligands (CXCL1 and CXCL2), chemokines that attract MDSCs to the tumor via CXCR2." (PMID 29703902, 2018). "Remarkably, the stromal and tumor expression of CXCL2, together with CXCL1, is regulated by the exposure to pro-inflammatory cytokines, such as TNF-alpha." (PMID 30591657, 2018). "These cells express CXCR1 and CXCR2 at their surface and are recruited by their ligands including CXCL1 and CXCL2 which can be produced by tumor, endothelial cells or fibroblasts." (PMID 29983866, 2018). "Here, we focused on CXCL1 and CXCL2, which function as chemokines to attract MDSCs to the tumor, since Snail knockdown attenuated intratumoral MDSC which suppressed CD8+T cell proliferation." (PMID 29703902, 2018). "Neutrophils are attracted by various ligands including CXCL1, CXCL2, CXCL5 to tumor site and play central roles as tumor-associated neutrophil (TAN) in tumor inflammation and development from initiation to metastasis." (PMID 30220913, 2018). "Two other cytokine gene expressions evolved in the same way, Cxcl1 and Cxcl2, suggesting that these chemotactic factors for neutrophil recruitment are produced by TAMs and/or tumor cells in response to inflammatory stimuli." (PMID 29662647, 2018). "Consistent with patterns of heavy Ly6Ghi gMDSC infiltration, MOC1 tumors expressed increased transcript levels of CXCR2 and the CXCR2 ligands CXCL1 and CXCL2, with a significant increase in expression between days 10 and 20 of tumor progression." (PMID 28915554, 2017). "The results showed that several genes were highly expressed in tumor, including Cxcl2, Ccl2, Ccl3, Ccl4, and Ccl5." (PMID 28432279, 2017). "Our results demonstrate that HVJ-E combined with poly I:C or CXCL2 induced a neutrophil-mediated anti-tumor effect in various mouse tumor models, suggesting the potential wide spectrum of this anti-tumor mechanism." (PMID 27259252, 2016). "Among them, we selected five decreased (CCDC28B, SREK1IP1/P18SRP/SFRS12IP1, RASL10B, PHF21A/BHC80 and PGC) and two increased genes (IL-11 and CXCL2), by microarray, as differentiation-, splicing-, inflammation-, or tumor-related genes." (PMID 26701885, 2016). "Treatment of tumor-bearing IFN-deficient mice with recombinant murine IFN-β downregulated CXCL1 and CXCL2 expression in blood and tumor to the levels observed in control mice." (PMID 28066438, 2016). "Low CXCL1 or CXCL2 level in BM and high level of these chemokines in the tumor form gradient in tumor-bearing mice, thus attracting neutrophils into tumor site." (PMID 28066438, 2016). "Through cancer treatment using HVJ-E+poly I:C, we conclude that TANs are recruited by CXCL2 to exert anti-tumor activity in the TME in response to HVJ-E treatment." (PMID 27259252, 2016).
tumor (continued). "CCL2, CXCL1 and CXCL2 expressed by IECs, stromal and tumor cells during CRC possess pro-tumoral capacities since they chemoattract myeloid cells including neutrophils and tumor-associated macrophages, and stimulate angiogenesis." (PMID 27344176, 2016). "Regulation of the proangiogenic factor CXCL2 has been shown in tumor progression, vessel formation during tumor growth, and successful wound healing." (PMID 26701134, 2016). "Expression of CXCL1 and CXCL2 in blood and tumor was significantly higher in Ifnb1−/− mice as compared to wild-type (WT) controls." (PMID 28066438, 2016). "KaLwRij macrophages had increased proliferation and increased Chi3l3 (1.80 fold), Chi3l1 (2.48 fold), and Cxcl2 (3.45 fold) expression, transcriptional markers for pro-tumor M2 macrophage polarization." (PMID 26020268, 2015). "CXCL1, CXCL2 and CXCL3 are positively associated with tumor associated angiogenesis and depletion of these three chemokine factors have inhibited the tumor growth in mice." (PMID 26303932, 2015). "Gene silencing of SEMA7A in peritoneal elicited macrophages from DA-3 tumor-bearing mice resulted in decreased CXCL2/MIP-2 expression." (PMID 24550834, 2014). "When triggered by SEMA7A, macrophages elevate secretion of angiogenic CXCL2/MIP-2 while silencing SEMA7A resulted in decreased tumor angiogenesis, and lower levels of CXCL2/MIP-2, CXCL1 and MMP-9." (PMID 25071604, 2014). "Mast cells will also release TNFα, known to help deliver oxygen to hypoxic areas of the tumor allowing for tumor growth, and release CXCL2, seen to induce melanoma cell proliferation." (PMID 24949488, 2014). "We therefore tested to see if SEMA7A gene silencing in tumor cells has an effect on CXCL2/MIP-2 chemokine expression." (PMID 24550834, 2014). "Immunohistochemical analysis detected CXCL2 protein expression in infiltrating inflammatory cells and some tumor cells after AOM and DSS treatment." (PMID 23272179, 2012). "al. further suggest that tumor-infiltration by neutrophils is at-least partly mediated by autocrine CXCL-2 production." (PMID 22348096, 2012). "As observed for PDT-treated tumor cell lines, Cxcl2, Cxcl3 and Il6 were among the most strongly upregulated genes, although we cannot exclude that these cytokines were expressed by stromal cells in the tumor microenvironment or tumor-associated immune cells." (PMID 21738796, 2011). "Mechanistically, this subset responds to hypoxia by expressing VEGFA to directly promote tumor angiogenesis while highly expressing the chemokines CXCL2, CXCL3, and CXCL8 to establish a chronic inflammatory microenvironment that indirectly fosters tumor progression and vascularization." (PMID 41514936, 2026). "Notably, several soluble factors associated with NET induction, including CXCL2, CXCL8, and IL‐6, were markedly upregulated in PUS7‐overexpressing tumour cells compared with controls." (PMID 41496500, 2026). "In this regard, we speculated that due to the significant increase in the number of tumor‐infiltrating neutrophils compared to other immune cells, neutrophils became the main cell type influenced by cholesterol under CXCL2 overexpression." (PMID 41114470, 2026). "Furthermore, our clinical samples revealed a substantial decrease in CXCL2 protein levels in HCC tissues than those in adjacent non‐tumor tissues." (PMID 41114470, 2026). "Additionally, they decreased the release of CXCL2/GROβ, which is linked to myeloid cell infiltration in metastatic sites, and DKK1, OPG, and IL-6, factors that promote endothelial network formation and tumor cell migration." (PMID 40688675, 2025). "Therefore, the correlation of SERPINA3 and CXCL2 expression with M1/M2 polarized macrophage infiltration in PCa was validated using QUANTISEQ methods in the Timer2.0 tumor immune infiltration-related database." (PMID 40367014, 2025). "CXCL2/CXCR2 axis in tumor-infiltrating myeloid-cells was highly context-dependent." (PMID 40087771, 2025).
tumor (continued). "Furthermore, distinct monocyte subpopulations directly contribute to metastatic progression through CXCL2-mediated interactions with circulating tumor cells." (PMID 40900791, 2025). "CAF release of chemokine (C-X-C motif) ligand 1 and 2 (CXCL1 and CXCL2) also increases tumor invasion, with CXCL12 further increasing macrophage recruitment, and CXCL1 increasing tumor invasion via activation of matrix-metallopeptidase 1 (MMP1), also known as interstitial collagenase." (PMID 40872475, 2025). "Additionally, studies have shown that a tumor adaptation mechanism exists whereby the Ccl2/Ccr2/Cxcl2 axis promotes the recruitment of monocytes which in turn can acquire pro-tumorigenic phenotypes and contribute to immunosuppression." (PMID 40568084, 2025). "Thus, our data indicate that GSDMC2/3/4 promote the expression of CXCL2, which facilitates the recruitment of MDSCs into the tumor microenvironment." (PMID 40213993, 2025). "Notably, tumor cells were the exclusive source of overexpressed Ccl5 and Cxcl2, while Ccr5 + NK cells and Cxcr2 + macrophages were enriched in the NLRP4-OE TIME, a pattern that persisted throughout tumor progression." (PMID 40087771, 2025). "To assess the functional relevance of these findings, we tested whether knockdown of CCL5 and CXCL2 in tumor cells (OE_shCCL5_shCXCL2) could abrogate the anti-tumor effects of NLRP4-OE." (PMID 40087771, 2025). "Moreover, there is growing interest in the role of CXCL2 in mediating the polarization of macrophages towards the M1 phenotype in the tumor microenvironment." (PMID 40367014, 2025). "On the other hand, TIL-secreted IL-22 prompted CRC to recruit anti-tumor TAN through CXCL2." (PMID 40087771, 2025). "For example, targeting the vascular endothelial RBPJ/CXCL2 axis may reduce the tumor-promoting effects of TAMs." (PMID 39068459, 2024). "Furthermore, an intriguing observation in multi‐primary tumours was the enhanced interaction between CXCL2/3/5/8 in macrophages and CXCR1/2 in neutrophils that has been previously reported to play critical roles in forming NETs in human neutrophils." (PMID 39601163, 2024). "Additionally, transformed mesenchymal stromal cells secrete CXCL2, which promotes the infiltration of M2 macrophages and the metastasis of tumor cells." (PMID 39100676, 2024). "In HCC, CXCL2 and its family members can shape the tumor microenvironment." (PMID 39770551, 2024). "Moreover, the induction of M2-type polarization of TAMs by neuroblastoma tumor cells upregulates CXCL2 secretion in TAMs, which enhances tumor cell invasion." (PMID 38927907, 2024). "In addition, the tumor tissues were lysed, and the p-p65, p65, and CXCL2 levels were detected by western blot." (PMID 38637499, 2024). "The high expression of CXCL2 can facilitate the metastasis of diverse malignant tumor cells." (PMID 38637499, 2024). "However, the existing research on the intricate upstream and downstream signaling networks of CXCL2 needs to be improved, necessitating further investigation to augment our comprehension of tumor progression." (PMID 38637499, 2024). "In addition, we applied the TISIDB database to establish a detailed relationship between the expression of CXCL2/12/14/17 and the abundance of 28 distinct tumor-infiltrating lymphocytes subsets." (PMID 38232115, 2024). "CXCL-2 is produced by various cell types, including stromal cells, ECs, and tumor cells." (PMID 39796700, 2024). "On the contrary, CXCL5, CXCL1 and CXCL2 have a tumor-promoting effect because they recruit MDSCs, which can play an immunosuppressive role by suppressing the immune function of lymphocytes through the secretion of Arg-1 and iNOS, and CXCL1 and CXCL2 also reduce the number of CD8+ T cells." (PMID 39007138, 2024). "CXCL2 attracts immune cells to the tumor site, and VEGF signaling may induce CXCL2 secretion by TAMs and other cell types." (PMID 39770551, 2024).
tumor (continued). "Key signaling molecules, including transforming growth factor beta (TGFβ) related to SRC, interleukin 1 (IL-1) associated with FOS, CXC chemokine (CXCL2), and vascular endothelial growth factor (VEGF), were highlighted due to their critical roles in tumor initiation, progression, and deterioration." (PMID 39770551, 2024). "Interestingly, supernatant of platelet-tumor cell coculture contained CXCL2, CXCL5, CXCL7 and activated neutrophil migration." (PMID 38786066, 2024). "A prior investigation showed that the overexpression of CXCL1 and CXCL2 by interleukin 6 can enhance the recruitment of monocytes and drive macrophages towards a protumor phenotype, ultimately leading to the formation of a suppressive tumor microenvironment." (PMID 38214842, 2024). "Importantly, qRT-PCR and immunofluorescence analyses also revealed that double treatment, with both a-Egfl6 and a-PD-L1, reduced tumor expression levels of both IL-10 and Cxcl2." (PMID 39312740, 2024). "CXCL2 and CXCL8 are two types of chemokine (C-X-C motif) ligand (CXCL), which are generally produced by monocytes and can recruit neutrophils to accumulate in the tumor environment, causing immunosuppression and promoting cancer production and progression." (PMID 38582791, 2024). "Only CXCL2 was equally high expressed in iCAFs from all tumor samples." (PMID 39516494, 2024). "Interestingly, monocytes required intact Notch signaling in ECs to acquire MDSC phenotypes and functions in the tumor, and EC-derived CXCL2 was a sufficient factor priming monocytes to complete differentiation into MDSCs." (PMID 38786066, 2024). "Possibly, CXCL2 production may be initiated by tumor epithelial cells and then enhanced through CAFs and recruited TANs, similar to previously discussed chemokines." (PMID 38339310, 2024). "CXCL2 is primarily synthesized by tumor cells, neutrophils, and macrophages." (PMID 38637499, 2024). "Furthermore, IL-1β was identified as a promoter of vascular endothelial growth factor (VEGF) and C-X-C motif chemokine ligand 2 (CXCL2) expression, which are both crucial for tumor growth and metastasis." (PMID 38066523, 2023). "Another conclusion is that CXCL2 and PPBP may be associated with the inhibition of proliferation in the tumor, but only in some types of tumors." (PMID 37686093, 2023). "Some results have shown that the expression of CXCL2 is associated with NF-κB activation involved in tumor invasion and metastasis, and the chemokine CXCL12 recruits immune cells infiltrating cancerous foci and triggers tumor-associated inflammation." (PMID 37994159, 2023). "The expression of CXCL2 is often decreased in the tumor compared to healthy tissue." (PMID 37686093, 2023). "The increased secretion of CCL2 and CXCL2 may have accounted for the enhanced migration of MDSCs in the peritoneal cavity of tumor-bearing METTL3-cKO mice." (PMID 37932814, 2023). "CXCL2 is crucial in neutrophil recruitment into the tumor tissue." (PMID 37540227, 2023). "Protein-protein interaction (PPI) analysis revealed that cyclin B1 (CCNB1), mitotic arrest deficient 2 like 1 (MAD2L1), H2A family member Z (H2AFZ) and CXCL2 may be the important protein molecules involved in CXCL3-related tumor biology." (PMID 38031087, 2023). "In order to investigate the effects of PRSS35 degradation of CXCL2 on neutrophil activity in tumor progression in vivo, we generated Hepa1-6 cell lines that stably expressed mPRSS35, mCXCL2, both, or an EV control and separately inoculated these lines subcutaneously into C57BL/6J mice." (PMID 36934105, 2023). "WB analysis confirmed the inhibitory effects of PRSS35 on CXCL2 protein levels in tumor tissues." (PMID 36934105, 2023). "Additionally, CXCL2 promotes neutrophil polarization within the tumor towards the TAN 2 phenotype, thus facilitating cancer progression." (PMID 37540227, 2023). "Tumor invasion is closely linked to the chemokines ligand 1 (CXCL1) and ligand 2 (CXCL2)." (PMID 37237548, 2023).
tumor (continued). "Concerning CXCL2, its participation has been constantly related to different types of cancer such as prostate, colon, and bladder, allowing a better understanding of its role in the tumor microenvironment." (PMID 37893029, 2023). "Moreover, increasing evidence indicates that CXCL2 is also involved in tumor initiation and progression." (PMID 36276119, 2022). "Hence, we analyzed the relationships between the signature and TIP-related genes, and the results showed that cold tumor genes such as CXCL2 and CCL20 and hot tumor genes such as CXCR3, CXCL11, and PDCD1 were upregulated in the high-risk group in both cohorts." (PMID 35938001, 2022). "Additionally, treatment with pCSs significantly decreased the concentration of CXCL2 in the circulating blood to an undetectable level in B16F10 tumor‐bearing mice (tumor size ≈200 mm3)." (PMID 35343112, 2022). "Together, these findings suggested that ferroptosis-related gene CXCL2 may regulate tumor immune response to influence cancer development and serve as a biomarker for diagnosis and prognosis in patients with HCC." (PMID 36276119, 2022). "In addition, the expression of CXCL9/10/11/13 in primary tumor samples was remarkably higher than normal samples, whereas CXCL2/3/4/6/7/8/12/17 transcription levels were significantly lower (all P < 0.05)." (PMID 35725915, 2022). "Thus, the increased expression of APCS, IL-6, and CXCL2 found in our patient cohort corresponds with improved immune cell function, and subsequent delays in VS tumor recurrence." (PMID 36195959, 2022). "We found that CXCL2 attracted M2-type macrophages to infiltrate and promote tumour metastasis." (PMID 35541899, 2022). "Furthermore, CXCL2 expression was obviously correlated with the immune signatures, including tumor-infiltrating immune cells and immunostimulators." (PMID 36276119, 2022). "Previous research found that the tumor-associated MSCs produced chemokines Gro-α/CXCL1, Gro-β/CXCL2, and IL8, which bound to the CXCR1/2 receptor on the surface of tumor cells and led to the formation of chemoresistance and induced the polarization of macrophages." (PMID 36354566, 2022). "CD204+ macrophages were the second most abundant tumor infiltrating immune cell, and when comparing to normal oral mucosa, two differently expressed genes linked to tumor associated macrophages and myeloid derived suppressor cells (MDSC) were identified: CXCL2, CD70." (PMID 36698398, 2022). "Therefore, SNAIL enriched the infiltration of macrophages by promoting EMT and CXCL2 secretion, and the infiltration of macrophages was an important factor in promoting tumour proliferation and migration." (PMID 35541899, 2022). "CXCL2 has also been demonstrated to recruit MDSCs and promote tumor growth in breast cancer, pancreatic ductal adenocarcinoma, oral cancer, and glioblastoma, whereas knockdown of CXCR2 in MDSCs and knockdown of CCL2 reduced the recruitment of MDSCs to tumor sites in mice." (PMID 35854339, 2022). "CXCL2 expression was also significantly higher in tumours than adjacent tissues." (PMID 35541899, 2022). "We found that SNAIL overexpression promoted the EMT of tumours and the expression of CXCL2." (PMID 35541899, 2022). "A high CXCL2 expression is correlated with the tumor stage and patient prognosis." (PMID 36290882, 2022). "We then analyzed the associations between CXCL2 expression and classical macrophage phenotype markers of M0 (undifferentiated) (AIF1), M1 (anti-tumor) (IL12A, TNF, NOS2, PTGS2) and M2 (tumor-promoting) (IL10, CD163, TGFB1, CSF1R) in TCGA-LIHC cohort with Spearman’s rank correlation test." (PMID 36276119, 2022). "The overexpression of CXCL2 promotes CRC tumor progression and liver metastasis." (PMID 35954156, 2022).